GAGE10 (G antigen 10)
Synonyms: GAGE-10; OTTHUMG00000024136
Tractability: No criterion of Open Targets' tractability assessment is met for any kind of drug.
Gene: Protein-coding gene on chromosome X (49,303,646 to 49,319,841, forward strand). Ensembl gene ENSG00000215274.
Subcellular location (Human Protein Atlas): Plasma membrane; Cytosol; Golgi apparatus
Gene Ontology:
Molecular function: protein binding
Homologues: Orthologues: chimpanzee GAGE10 (90% identical). Paralogues in human: GAGE13 (93% identical), GAGE2A (92% identical), GAGE1 (91% identical), GAGE12F (91% identical), GAGE12G (91% identical), GAGE12J (91% identical), GAGE12C (91% identical), GAGE12D (91% identical), GAGE12E (91% identical), GAGE12H (90% identical), GAGE2E (85% identical), PAGE1 (59% identical), and 10 more.
Diseases named in the same sentence as GAGE10 in open-access papers:
GAGE10 is named in the same sentence as 1 disease in open-access papers, as found by Europe PMC text mining. Sharing a sentence is not in itself a finding about the gene and the disease. The quoted sentences say what the papers report.
cancer (2 papers, 2017 to 2019). A tumor composed of atypical neoplastic, often pleomorphic cells that invade other tissues. "The site with the greatest absolute age-DNAm correlation difference between males and females mapped to GAGE10, a member of the GAGE cancer/testis antigen family." (PMID 31892350, 2019).